NPY (neuropeptide Y)
Diseases named in the same sentence as NPY in open-access papers (continued):
Sharing a sentence is not in itself a finding about the gene and the disease.
Obesity (continued). "Therefore, treatments that decrease NPY expression or block NPY receptor signaling may be effective in treating obesity." (PMID 41151834, 2026). "The aim of this study was to investigate the effects ofquercetin on obesity and ovarian tissue by analyzing the expression of genesinvolved in the hypothalamus-pituitary-gonadal axis, includingob-Rb, ob-Ra, and brain-derived neurotrophic factor(Bdnf), neuropeptide Y (NPY), andKisspeptin (Kiss-1)." (PMID 39983030, 2025). "In addition to evaluating NPY’s excessive hypothalamic expression resulting from EMF at the level of stress response, it is conceivable that it may cause obesity in later life stages due to its orexigenic effects." (PMID 40636869, 2025). "While activating ARC AgRP/NPY neurons has been shown to be both aversive and rewarding depending on the duration of activation, the positive valence associated with inhibiting ARC AgRP/NPY neurons lends itself well to targeting these neurons for obesity drug development." (PMID 39644359, 2025). "The rationale for this choice is that the oral hypoglycemic drug metformin is efficacious for the treatment of obesity consequent to type 2 diabetes, and that the principal targets of metformin include the liver (insulin functional agonism) and the brain (reduction of NPY orexigenic signals)." (PMID 38191558, 2024). "Notably, individuals with obesity tend to have higher concentrations of fasting plasma NPY." (PMID 39722170, 2024). "Overall, we hypothesized that DNMT1, Bsx and NPY might be involved in triggering dysfunctional differentiation of hypothalamic NPCs in FGR rat offspring, which directly led to the increased susceptibility to obesity in adulthood." (PMID 37378669, 2024). "CAMKK2 null mice developed obesity, insulin resistance, and less glucose tolerance with standard chow whereas displayed a considerably smaller increase in adiposity and adipocyte size with high-fat diet compared with WT mice by regulating NPY and therefore affecting appetite." (PMID 38469147, 2024). "However, studies in mice with obesity showed NPY concentration on blood was found to be higher." (PMID 37460969, 2023). "Taken together, targeting NPY could be a plausible intervention for human obesity." (PMID 37761913, 2023). "Dysregulation of the neuropeptide Y system, as occurs in metabolic diseases like obesity, may lead to mitochondrial dysfunction and, consequently, to oxidative stress and to the white adipose tissue inflammatory environment, contributing to the development of a metabolically unhealthy profile." (PMID 36830982, 2023). "Even though NPY has been related with lipid and adiposity abnormalities, which have a key role in NAFLD development, the mechanism of the regulatory effects of NPY is still unknown; however, an NPY antagonist could be a novel target in pharmacological options for obesity and NAFLD." (PMID 37753211, 2023). "Thus, changes in NPY levels may precede obesity and be one of the main driving factors for its development." (PMID 36830982, 2023). "Indeed, patients with obesity have higher levels of NPY which may promote higher food intake and lower energy expenditure." (PMID 36830982, 2023). "POMC and NPY could, therefore, be used as pharmaceutical targets for reversing obesity." (PMID 37899888, 2023). "Our study indicates that local-macrophage-derived NPY may also impact the pathogenesis of obesity." (PMID 37834391, 2023). "Moreover, feed deprivation in rodents has been shown to up-regulate the hypothalamic expression of NPY to incite feed intake and maintain homeostasis, while rats subjected to repeated administration of NPY show hyperphagia and increased body weight gain leading to obesity." (PMID 35448669, 2022). "Neuronal architecture in the hypothalamus, involving neuropeptide Y (NPY) fibres and expression of neuropeptides and factors of the mTOR signalling pathway, takes part in the mechanisms protecting the males and predisposing Leu-females to obesity under the appropriate environment." (PMID 35806240, 2022).
Obesity (continued). "Thus, NPY antagonism in macrophages may represent a potential therapeutic target for the treatment of obesity and fatty liver disease." (PMID 34829968, 2021). "However, differences in the distribution of serum NPY levels in obese phenotypes (including metabolically unhealthy obesity (MUO) phenotype and metabolically healthy obesity (MHO) phenotype) and the association of NPY with MUO phenotype have not been unequivocally established." (PMID 32831640, 2020). "Thus, a hypothesis to be tested is that obesity-induced falls in progesterone, especially if associated with increases in estrogen, decreases ArcN AT1R expression, and its ability to suppress NPY sympathoinhibition." (PMID 32160920, 2020). "Therefore, a HFD and obesity may cause sympathetic overactivity in a sex-specific manner through its modifications of POMC neurons, NPY neurons, and PVN glutamatergic neurotransmission." (PMID 32160920, 2020). "However, the occurrence of obesity involves a complicated synergy between extravagant food intake or reduction in energy expenditure, where the NPY system has been recognized as a critical player in the regulation of energy balance and pathophysiology of obesity." (PMID 33123166, 2020). "Here, the authors show that neuropeptide FF receptor-2 signalling promotes thermogenesis via control of NPY expression in the arcuate nucleus, and that it absence in mice leads to a failure of activation of diet-induced thermogenesis and the development of exacerbated obesity." (PMID 30413707, 2018). "In addition, in the absence of NPY, the obesity and sterility normally exhibited by leptin-deficient ob/ob mice were attenuated, indicating that NPY functions as a central effector of leptin deficiency." (PMID 29976877, 2018). "To this end, we aimed to test the anti-obesity effects of chronic treatment with a specific Y2-receptor antagonist with a potential clinical application to be obesity and metabolic disorders due to NPY excess induced by chronic stress or genetic factors (gain-of-function polymorphisms)." (PMID 29674968, 2018). "Therefore, therapeutic strategies which target the NPY system in peripheral tissue may facilitate intervention for obesity." (PMID 29109742, 2017). "Among those, the genes encoding the neuropeptide Y (NPY), two glutamate receptors (GRIK1, GRM7), the X-linked gastrin-peptide receptor (GRPR), and the organic anion transporter (SLCO4C1) are novel obesity candidate genes that may contribute to highly penetrant forms of familial obesity." (PMID 28489853, 2017). "Therefore, neuropeptide Y serves as the most potent appetite stimulator, which can reduce energy consumption and may play a key role in the onset of both obesity and type 2 diabetes mellitus." (PMID 27867820, 2016). "However, it could be difficult to conclude from the present data whether insulin resistance in the NPY overexpression group was a result of direct or indirect effects through obesity." (PMID 25993471, 2015). "Moreover, the epigenetic regulation of NPY might suggest that the overexpression is reversible via environmental stimuli and thus obesity development could be avoided if early counteracted." (PMID 26106286, 2015). "However, in a stress-induced obesity model, NPY induction in fat correlated with insulin resistance that could be attenuated by blockage of the Y2 receptor." (PMID 25993471, 2015). "Therefore, a better understanding of the mechanisms of how NPY influences body adiposity may facilitate therapeutic interventions for obesity." (PMID 24959194, 2014). "Whether NPY can be used as a biomarker for obesity awaits further determination." (PMID 24959194, 2014). "Thus, it is reasonable to speculate that the activation of I1R by allantoin may mediate leptin to inhibit hypothalamic NPY for reduction of hyperphagia to result in the decrease of obesity." (PMID 23606885, 2013). "Macrophage derived NPY may participate in the connections between stress and obesity." (PMID 23472120, 2013).
Obesity (continued). "Administration of NPY into different brain regions, including the hypothalamus, frontal cortex, hindbrain, and hippocampus, induces hyperphagia (even in a satiated state), decreased sympathetic activity and thermogenesis, increased fat deposition, and promotion of weight gain and obesity." (PMID 22848202, 2012). "Chemogenetic activation of NTSGLP−1 significantly suppressed appetite, mitigated obesity, and modulated hypothalamic pro-opiomelanocortin (POMC) and neuropeptide Y (NPY)." (PMID 41508004, 2026). "Activation of hypothalamic GLP-1 receptors enhances satiety signaling by influencing neurons that express pro-opiomelanocortin (POMC) and neuropeptide Y (NPY), mechanisms that reduce excessive food intake and the metabolic load tied to obesity." (PMID 41010364, 2025). "The neuropeptide Y (NPY) system is believed to play a crucial role in regulating energy balance and contributing to the pathophysiology of obesity." (PMID 40357063, 2025). "Understanding the role of NPY at SFO is important then, especially in light of the co-occurrence of obesity and cardiovascular disturbances." (PMID 40308261, 2025). "Neuropeptide Y (NPY) and its receptor NPY2R are crucial in regulating appetite control, particularly in the context of obesity and diabetes in the hypothalamus." (PMID 38674857, 2024). "After treatment, changes in obesity indicators, such as BMI, waist circumference, WHR, NPY, and ADP were observed, and their clinical significance was analyzed." (PMID 38050318, 2023). "A HFD in obesity promotes histone acetylation of genes such as POMC and NPY, which regulate appetite and the dysregulation of which further perpetuates obesity." (PMID 36830032, 2023). "It is inferred from this that obesity plays a role in SNA inhibition and it is due to tonic activity of NPY, which further reveals an elevated α-MSH excitation." (PMID 36899905, 2023). "Recent studies show that the mechanisms contributing to the obesity of OLETF rats are leptin-independent and involve hypothalamic NPY neurons." (PMID 37298724, 2023). "Leptin positively regulates these SNS neurons through MBH-localized AgRP/NPY-, POMC/CART-, and SH2B-expressing neurons since deletion of LepR in those neurons results in obesity with the inefficiency of thermogenesis and lipolysis." (PMID 37547309, 2023). "We evaluated biochemical and hormonal parameters of bone mineral metabolism, including leptin and NPY, as well as bone histomorphometry, in an experimental model of high-fat diet (HFD)-induced obesity in rats before and after rWAT Dnx." (PMID 37630764, 2023). "Taken together, CB1 deficiency in dbh-positive cells upregulated NE signaling and decreased NPY signaling in the visceral WAT upon HFD treatment compared with the WT mice, thus protecting dbh-CB1-KO mice against HFD-induced obesity." (PMID 36293486, 2022). "NPY, cortisol, and OXT played a key role in directly propagated stress response to PTSD and obesity as well as in cascades recruiting other metabolic mediators." (PMID 35959009, 2022). "The existence of such a loop between the hypothalamic neuropeptide Y and BAT-derived IL18 in response to obesity and thermogenic activation is plausible and merits further investigation." (PMID 36482059, 2022). "Collectively, our study reveals the effect of NPFF on ARC NPY neuron activity in a human-based system, indicating the potential of targeting NPFFR2 for anti-obesity therapies." (PMID 35328681, 2022). "At the same time, ARC activates or inhibits neuropeptide Y (NPY) and agouti-related protein (AgRP) to control feeding behavior and energy metabolism, which is closely related to the onset of obesity and type 2 diabetes." (PMID 35525962, 2022). "Although stress upregulated both NPY and cortisol, the downstream effects of both markers are reported to relieve PTSD severity but exacerbate obesity." (PMID 35959009, 2022).
Obesity (continued). "The expression NPY-mRNA in macrophages is increased by HFD, which promotes metabolic inflammation to accelerate the development of obesity and NAFLD." (PMID 34829968, 2021). "Furthermore, this effect may be mediated by leptin, which inhibits NPY and is elevated in obesity." (PMID 33670342, 2021). "Subsequent catabolic effects and the impact on energy balance in terms of orexigenic signaling (e.g., via neuropeptide Y, NPY) further contribute to the maintenance of obesity and its comorbidities." (PMID 33664656, 2021). "Previously, promoter methylation of obesity-related genes including LEP, NPY, and LEPR was involved in tumorigenesis of renal cell carcinoma, and LEPR methylation was associated with prognosis, and predicted renal cell carcinoma recurrence." (PMID 33485366, 2021). "The purpose of the study was to assess the serum levels of NPY and PYY in adolescents with anorexia nervosa (AN) or obesity (OB), as well as in a healthy control group (CG)." (PMID 33670342, 2021). "We have previously investigated the contribution of NPY and POMC systems in obesity-induced hypertension and activation of RSNA in adult rabbits on a 3-week HFD." (PMID 34248679, 2021). "It has been well-documented that leptin exerts an inhibitory effect on food intake and increases energy consumption via suppressing the NPY/AgRP neurons and activating α-MSH/CART neurons in the hypothalamus, thus effectively reversing obesity." (PMID 33868169, 2021). "Even moderate overexpression of ARC NPY, and likely underexpression of POMC, is sufficient to induce overfeeding and obesity." (PMID 33138074, 2020). "Further research employing normal-weight controls as well as the consideration of hormonal status or menstrual cycle phase are required to better understand the role of NPY, PYY and PP in the pathophysiology of obesity and the emotional response to stress." (PMID 33192409, 2020). "Obesity in girls leads to decreased levels of neurotensin relative to eutrophic girls (p = 0.0035), while boys with obesity showed lower levels of MCH (p = 0.0002) and higher NPY content (p = 0.06), as compared to eutrophic boys." (PMID 33644105, 2020). "For example, leptin and insulin interact with hypothalamic neuropeptides NPY, MCH, and α-MSH, not only regulating appetite, but also activating the SNS, possibly contributing to obesity-related hypertension." (PMID 33644105, 2020). "Elevated hypothalamic NPY and decreased POMC are thought to promote the development and maintenance of obesity." (PMID 32545529, 2020). "The beta-catenin in the hypothalamus also affects NPY and POMC neurons, which suggests that the Wnt pathway regulates obesity by controlling food intake behaviour." (PMID 31540087, 2019). "A DBS neuromodulation approach of the ARC to treat obesity would preferably activate selectively the anorexigenic POMC and/or inactivate the orexigenic AgRP/NPY neurons." (PMID 31057350, 2019). "The relevance of NPY and its role, in combination with other regulatory peptides (POMC, AgRP, MC4-R and SOCS3), was clearly seen in adulthood, when obesity was settled in L-females." (PMID 29329236, 2018). "NPY overexpression in the DMH contributes to hyperphagia and obesity of rats, whereas knockdown of DMH NPY ameliorates these alterations." (PMID 29896090, 2018). "We have proposed an etiological role for NPY in the DMH in the development of hyperphagia and obesity of OLETF rats due to a deficit in the control of DMH NPY in these animals." (PMID 28575002, 2017). "GABAB agonists, such as baclofen, showed the ability to decrease neuropeptide Y (NPY), demonstrating an anti-obesity effect as this decreases human body weight and waist circumference." (PMID 26987061, 2016). "Chronic icv infusion of TTR in Otsuka Long-Evans Tokushima Fatty rats reversed hyperphagia and obesity and reduced DMH NPY levels." (PMID 27053000, 2016).
Obesity (continued). "In previous works, under diet-induced obesity (DIO) conditions, orexigenic neuropeptides (AgRP and NPY) were induced while anorexigenic neuropeptides (α-MSH) were reduced by hypothalamic ER stress." (PMID 26901224, 2016). "Overexpression of NPY in the DMH increases food intake and body weight, leading to obesity and type 2 diabetes in the Otsuka Long Evans Tokushima fatty (OLETF) rats." (PMID 26379628, 2015). "This study using mice provides strong evidence that up-regulation of NPY secretion and NPY2R expression within visceral fat contributes to obesity and metabolic syndrome in mammals." (PMID 26445145, 2015). "Overexpression of NPY in the dorsomedial hypothalamus, a major site of signaling from ARC neuronal projections, induces hyperphagia and obesity in rats." (PMID 26237477, 2014). "Increased NPY synthesis and secretion and reduced expression of POMC and its cleaved product α-MSH are characteristic of various models of obesity." (PMID 25258479, 2014). "The expression of NPY and NPYR2 can be induced in macrophages, platelets, nerves, and adipocytes by stress or genetically- or high fat diet-induced obesity in mice." (PMID 24959194, 2014). "In average, a 3-fold increase in NPY expression in the ARC and release in the PVN is observed in rodent models of obesity, including Zucker rats and the db/db and ob/ob mice." (PMID 21799827, 2011). "Paradoxically, chronic stress-induced over-activation of the negative feedback regulation of NPY and the “exercise-NPY” production mechanism can lead to excessive NPY release into adipose tissue, resulting in obesity and metabolic syndrome." (PMID 39931288, 2025). "Based on these findings, the authors proposed that NPY contributes to the development of the syndrome in women, regardless of obesity." (PMID 40871560, 2025). "In NPY-GFP::LIC::Ai9 reporter mice, we observed a subset of AgRP neurons that was LepR negative, suggesting a potential role of this subset in promoting obesity." (PMID 40540394, 2025). "Background and Objectives: Neuropeptide Y (NPY) family peptides and dipeptidyl peptidase-4 (DPP-4) are involved in gastrointestinal regulation and may contribute to obesity and type 2 diabetes mellitus (T2DM) pathophysiology." (PMID 40142315, 2025). "In mice with high-fat diet (HFD)-induced obesity, BBR administration increased GLP-1 receptor (GLP-1R) and orexin A expression while decreasing brain neuropeptide Y (NPY) expression, leading to reductions in body weight, plasma lipid levels, and insulin resistance." (PMID 40650060, 2025). "In the stress-induced obesity network, CCK inhibits NPY, which regulates the feeding behavior." (PMID 39062927, 2024). "In obesity, the SNS-stimulating action of leptin depends on a functional AngII type 1a receptor (AT1aR), which tonically suppresses inhibitory neuropeptide Y (NPY) input to POMC neurons within the ArcN and/or the presympathetic neurons in the periventricular nucleus." (PMID 38186879, 2024). "Orexigenic neuropeptide Y (NPY) neurons within the hypothalamus can stimulate feeding and suppress energy expenditure, and dysregulation of these neurons may contribute to obesity." (PMID 37761913, 2023). "This information is relevant because, in subjects with obesity with leptin receptor resistance, the lack of signaling in bone cells and the reduction or inhibition of neuropeptide Y can contribute to deleterious effects on bones." (PMID 36831188, 2023). "Finally, we observed higher levels of serum and hypothalamic NPY in HFD rats, corroborating clinical and experimental data in obesity conditions." (PMID 37630764, 2023). "Further, these alterations in gut microbiota have been shown to promote important changes in satiation signals including gut hormones (leptin, ghrelin, GLP-1, peptide YY and CCK) and orexigenic and anorexigenic neuropeptides (AgRP, NPY, POMC, CART) that influence hyperphagia and therefore obesity." (PMID 37571301, 2023).